HAAO (3-hydroxyanthranilate 3,4-dioxygenase)
Description:
Catalyzes the oxidative ring opening of 3-hydroxyanthranilate to 2-amino-3-carboxymuconate semialdehyde, which spontaneously cyclizes to quinolinate.
Synonyms: 3-HAO; h3HAO; HAO; VCRL1
Tractability: Small molecule: it has a binding pocket of medium quality. PROTAC: its protein half-life has been measured; a small molecule that binds it is known.
Target class: Enzyme; Oxidoreductase
Gene: Protein-coding gene on chromosome 2 (42,765,709 to 42,792,941, reverse strand). Ensembl gene ENSG00000162882.
Subcellular location: Cytoplasm, cytosol
Pathways (Reactome):
Metabolism: Tryptophan catabolism
Gene Ontology:
Molecular function: 3-hydroxyanthranilate 3,4-dioxygenase activity; ferrous iron binding; protein binding; electron transfer activity; iron ion binding; metal ion binding
Biological process: NAD+ biosynthetic process; neuron cellular homeostasis; quinolinate biosynthetic process; response to cadmium ion; response to zinc ion; 'de novo' NAD+ biosynthetic process from L-tryptophan; quinolinate metabolic process; L-tryptophan catabolic process
Cellular component: cytosol; cytoplasm
Genetic constraint (gnomAD): Loss-of-function variants: 42 observed, 35.19 expected, observed/expected ratio (o/e) 1.19, 90% interval 0.93 to 1.54. The upper end of that interval is the gene's LOEUF score, 1.54, which puts it in group 6 of 6, group 1 being the genes least tolerant of losing a copy. Missense variants: 383 observed, 322.47 expected, observed/expected ratio (o/e) 1.19, 90% interval 1.09 to 1.29. Synonymous variants: 148 observed, 123.03 expected, observed/expected ratio (o/e) 1.2, 90% interval 1.05 to 1.38.
Gene-disease validity (ClinGen):
ClinGen rates the evidence that HAAO causes each of these diseases.
vertebral, cardiac, renal, and limb defects syndrome 1 (autosomal recessive): Definitive.
Homologues: Orthologues: chimpanzee HAAO (98% identical), macaque HAAO (89% identical), rat Haao (87% identical), mouse Haao (85% identical), rabbit HAAO (85% identical), guinea pig HAAO (85% identical), pig HAAO (84% identical), dog HAAO (84% identical), tropical clawed frog haao (57% identical), zebrafish haao (54% identical), Caenorhabditis elegans haao-1 (38% identical).
Diseases named in the same sentence as HAAO in open-access papers:
HAAO is named in the same sentence as 42 diseases in open-access papers, as found by Europe PMC text mining. Sharing a sentence is not in itself a finding about the gene and the disease. The quoted sentences say what the papers report.
hypospadias (5 papers, 2020 to 2025). Hypospadias is the displacement of the urethral meatus on the ventrum of the penis. "The risk allele [T] of HAAO rs3816183 was associated with susceptibility to anterior/middle hypospadias (OR = 1.775, p=0.046)." (PMID 40547448, 2025). "GMDR analysis revealed a significant interaction between IRX6 rs6499755 and HAAO rs3816183 in the risk of hypospadias (cross-validation consistency = 10/10, testing balanced accuracy = 0.6065, p=0.0010)." (PMID 40547448, 2025). "In our study we found HAAO rs3816183 associated with hypospadias in both of European and Asian populations, however, we lacked the data of clinical subgroup analysis in European." (PMID 40547448, 2025). "By performing a meta-analysis, we found a significant association between IRX6 rs6499755/HAAO rs3816183 with the increased risk of hypospadias (ORs = 1.46, p < 0.00001; ORs = 1.23, p < 0.00001, independently)." (PMID 40547448, 2025). "Otherwise, we noted a significantly increased risk of anterior/middle hypospadias associated with HAAO rs3816183 [T] (ORs = 1.39, 95% Cl: 1.17–1.65, p=0.0002)." (PMID 40547448, 2025). "The result revealed a significant interaction between IRX6 rs6499755 and HAAO rs3816183 in the risk of hypospadias (cross-validation consistency = 10/10, testing balanced accuracy = 0.6065, p=0.0010)." (PMID 40547448, 2025). "Four included studies investigated the association between the risk alleles [T] of HAAO rs3816183 and susceptibility to hypospadias, indicating a significantly increased risk of hypospadias (ORs = 1.23, 95% Cl: 1.16–1.31, p < 0.00001)." (PMID 40547448, 2025). "We also observed that HAAO rs3816183 had an association with increased risk of anterior/middle (OR = 1.775, p=0.046) hypospadias, especially middle hypospadias (OR = 2.130, p=0.028)." (PMID 40547448, 2025). "In the Asian population, we observed the association between HAAO rs3816183 with anterior/middle hypospadias by subgroup analysis." (PMID 40547448, 2025). "The results of meta-analysis (including 3789 cases and 9241 controls) indicated that IRX6 rs6499755 and HAAO rs3816183 were significantly associated with hypospadias (both p < 0.00001)." (PMID 40547448, 2025). "The HAAO rs3816183[T] is associated with increased risk to anterior/middle hypospadias in Southern Han Chinese population." (PMID 35386263, 2022). "HAAO is a gene that encodes a protein, which catalyzes the synthesis of quinolinic acid, and has been identified as a risk gene for hypospadias." (PMID 35386263, 2022). "Stratification analysis to evaluate the association between HAAO rs3816183 T>C polymorphism and hypospadias susceptibility (by subgroup)." (PMID 35386263, 2022). "This is the largest Asian case–control study to investigate the association of HAAO polymorphism rs3816183 T>C with hypospadias susceptibility." (PMID 35386263, 2022). "We further performed a colocalization analysis of primary pQTL and GWAS signals and found that the lead pQTL variant of AKR1A1 and HAAO were colocalized with the GWAS variants associated with blood protein levels and hypospadias, respectively." (PMID 32778093, 2020). "The meta-analysis supported the hypothesis that IRX6 rs6499755 and HAAO rs3816183 were the susceptibility loci for hypospadias." (PMID 40547448, 2025). "The risk allele [T] of HAAO rs3816183 had an association with increased risk of middle (OR = 2.130, 95% CI = 1.072–4.232, p=0.028) and anterior/middle (OR = 1.775, 95% CI = 1.005–3.135, p=0.046) hypospadias." (PMID 40547448, 2025). "This case-control study was designed to investigate whether there is any meaningful relationship between IRX6 rs6499755 and HAAO rs3816183 polymorphisms with hypospadias in the Northern Han Chinese population, and try to find the corresponding risk alleles." (PMID 40547448, 2025). "Furthermore, the results of the meta-analysis support identified a strong relationship between the IRX6 and HAAO polymorphisms and hypospadias susceptibility in multiple populations." (PMID 40547448, 2025).
hypospadias (continued). "Moreover, GMDR analysis revealed a significant interaction between IRX6 rs6499755 and HAAO rs3816183 in the risk of hypospadias, which indicated the potential linkage disequilibrium." (PMID 40547448, 2025). "Our study aims to investigate whether IRX6 rs6499755 and HAAO rs3816183 polymorphisms are susceptible to hypospadias in Chinese Northern Han." (PMID 40547448, 2025). "HAAO is an enzyme that catalyses the conversion of 3-hydroxy-octylaminobenzoic acid (3-OH-AA) to quinolinic acid (QA), which has been identified as a risk gene for hypospadias." (PMID 40376698, 2025). "Association between HAAO rs3816183 T>C polymorphism and hypospadias susceptibility." (PMID 35386263, 2022). "Thus, this study was conducted to elaborate the association between HAAO gene polymorphism rs3816183 T>C and hypospadias in the largest hypospadias cohort from Asia, including 577 patients and 654 healthy controls in China." (PMID 35386263, 2022). "However, the HAAO rs3816183 polymorphism was only significantly associated with an increased susceptibility toward anterior/middle hypospadias susceptibility in the present study." (PMID 35386263, 2022). "Based on the stratified analysis of hypospadias subtypes, it was found that the HAAO risk allele rs386183[T] enhances the susceptibility for hypospadias among patients with anterior/middle hypospadias subtypes (adjusted OR = 1.31, 95% CI = 1.05–1.64, p = 0.017)." (PMID 35386263, 2022). "However, only HAAO rs3816183 T>C was significantly associated with an increased risk toward hypospadias." (PMID 35386263, 2022). "Thus, we conducted this study to validate the association of HAAO rs3816183 T>C polymorphism with hypospadias susceptibility." (PMID 35386263, 2022). "Our findings support the hypothesis that the mechanism underlying the variations in the HAAO gene may contribute to the pathogenesis of hypospadias and thus requires in-depth research." (PMID 35386263, 2022). "Similar genetic studies have suggested that rs3816183[T] HAAO polymorphisms may result in increased hypospadias susceptibility." (PMID 35386263, 2022). "Pathogenesis of hypospadias has been attributed to the incomplete fusion of the urethra in a portion of the penis and the expression of HAAO in male mouse genital tubercle." (PMID 35386263, 2022). "Second, in-depth exploration of HAAO rs3816183T>C and hypospadias sensitivity mechanisms is required." (PMID 35386263, 2022). "Nevertheless, the further biological mechanisms of IRX6 rs6499755/HAAO rs3816183 result in the increased hypospadias risks remain unclear." (PMID 40547448, 2025). "However, there was no statistically significantly associated with hypospadias risk observed in HAAO rs3816183 [T] polymorphism (all p > 0.05)." (PMID 40547448, 2025). "Therefore, our study demonstrated that HAAO rs3816183 polymorphism is not equally associated with hypospadias risk in different populations." (PMID 35386263, 2022). "Our results demonstrated that the SNPs rs3816183[T] in HAAO may be associated with increased anterior/middle hypospadias but not posterior hypospadias, suggesting that HAAO may influence distal part of penile urethral formation." (PMID 35386263, 2022). "Nevertheless, the results showed that the HAAO rs3816183[T] polymorphism may not be associated with hypospadias susceptibility in dominant and recessive models (adjusted OR = 1.19, p = 0.15/adjusted OR = 1.59, p = 0.06)." (PMID 35386263, 2022). "We hypothesized that the HAAO rs3816183 T>C polymorphism may disrupt the metabolism of its encoded protein leading to disorders of NAD synthesis, which contribute to the pathogenesis of hypospadias." (PMID 35386263, 2022). "The fact that there may be many complex causes for hypospadias and that the environmental and maternal factors were not accounted for in our study could be the reason that the HAAO rs3816183 variants was found to be associated only with anterior/middle hypospadias." (PMID 35386263, 2022).
hypospadias (continued). "In the subgroup of anterior/middle hypospadias, we observed a not significantly related with IRX6 rs6499755(ORs = 1.30, p=0.06) and a significantly associated with HAAO rs3816183 (ORs = 1.39, p=0.0002)." (PMID 40547448, 2025).
Cognitive impairment (3 papers, 2018 to 2021). Abnormal cognition is characterized by deficits in thinking, reasoning, or remembering. "They demonstrated that adjunctive antidepressant aripiprazole ameliorated depressive behavior and cognitive impairment in the ischemic mice via downregulation of IDO1, HAAO, QUIN, and ROS." (PMID 33192328, 2020). "The adjunctive antidepressant aripiprazole ameliorated depressive behavior and cognitive impairment in the PSD mice via downregulation of IDO1, HAAO, QUIN, and ROS." (PMID 30693061, 2018). "The beneficial effect of aripiprazole on depressive-like behavior and cognitive impairment may be mediated by inhibition of IDO1, HAAO, QUIN, and ROS." (PMID 30693061, 2018).
endometrial cancer (3 papers, 2023 to 2025). Primary or metastatic malignant neoplasm involving the endometrium (mucous membrane that lines the endometrial cavity). "Expression patterns of HAAO are variable among different cancer types; however, studies of endometrial carcinomas revealed promotor hypermethylation of HAAO is prominent and to be associated with microsatellite instability and poor clinical outcomes." (PMID 37876966, 2023). "Silencing HAAO expression is associated with endometrial cancer." (PMID 41282989, 2025). "Furthermore, the methylation level of HAAO was significantly correlated with disease-free survival in patients with endometrial cancer (P = 0.034)." (PMID 41282989, 2025). "Researchers found that the promoter of HAAO was highly methylated in 63% of endometrial cancer samples and that the methylated promoter resulted in the absence of HAAO expression." (PMID 41282989, 2025).
alcohol dependence (2 papers, 2012 to 2020). Physical and psychological dependence on alcohol. "Four genes, MAPK1 (marijuana dependence in black women), MANBA (alcohol dependence in white men), HAAO (cocaine dependence in white women), and IFNG (opiates dependence in white women), met the threshold by the gene-based method only." (PMID 23365539, 2012).
atherosclerosis (2 papers, 2021 to 2022). A disease characterized by the build-up of fatty material and calcium deposition in the arterial wall resulting in partial or complete occlusion of the arterial lumen. "Supplementation of 3HAA reduced the athero formation and blocking of HAAO (that catabolize 3HAA into other derivatives) by NCR-631 increased endogenous levels of 3-HAA, which reduced atherosclerosis." (PMID 34630411, 2021).
liver cancer (2 papers, 2023 to 2025). An epithelial or non-epithelial malignant neoplasm that arises from the liver. "Moreover, Kaplan–Meier survival analysis demonstrated that high expression of HAAO is associated with improved overall survival in patients with other types of cancers including breast, kidney, liver cancer, rectum adenocarcinoma, and others." (PMID 36627132, 2023). "As expected, IHC staining of HAAO was highly related to 4‐HNE staining in the human liver cancer tissue microarray." (PMID 36627132, 2023). "The data revealed that the expression level of HAAO in liver cancer is negatively correlated with ferroptosis‐resistant genes including SLC7A11, SLC3A2, and ACSL3, whereas positively correlated with ferroptosis‐sensitive gene ACSL1." (PMID 36627132, 2023). "HAAO expression is negatively correlated with anti‐ferroptosis genes such as SLC7A11, SLC3A2, and ACSL3, and high HAAO expression is associated with improved prognosis in cancers such as breast, kidney, and liver cancer." (PMID 40103267, 2025). "Notably, HAAO signaling intensity is lower in liver cancer than para‐cancer tissues, indicating HAAO is a potential tumor suppressor." (PMID 36627132, 2023). "Therefore, we employed the liver cancer as the model to test whether HAAO is correlated with ferroptosis signature in vivo." (PMID 36627132, 2023).
ovarian carcinoma (2 papers, 2020 to 2025). A malignant neoplasm originating from the surface ovarian epithelium. "Methylation of HAAO serves as a valuable prognostic marker in ovarian cancer (OC) and prostate cancer (PC), and loss of HAAO promotes cancer cells resistant to ferroptosis." (PMID 40821701, 2025).
posterior hypospadias (2 papers, 2022 to 2025). Posterior hypospadias is a rare, non-syndromic, urogenital tract malformation characterized by an ectopic urethral meatus opening located in the posterior penis, the penoscrotal junction, the scrotum or the perineum, which often appears stenotic. "However, no significantly increased risk of posterior hypospadias was found linked to IRX6 rs6499755 [C] and HAAO rs3816183 [T] (all p > 0.05)." (PMID 40547448, 2025).
brain inflammation (1 paper, 2022). "One would expect that inhibition of HAAO might cause an increase in the levels of upstream pronociceptive metabolites (such as 3-Hk); however, a previous study demonstrated lack of a massive accumulation of 3-Hk in the brain of Haao-null mice in an LPS model of brain inflammation." (PMID 36227694, 2022).
brain tumors (1 paper, 2022). "Contrastingly, the expression of the KP enzymes that lead to NAD+ synthesis, KYNU, HAAO, ACMSD, and QPRT were significantly increased in brain tumors compared to the brain cortex." (PMID 36355137, 2022).
epilepsy (1 paper, 2023). A brain disorder characterized by episodes of abnormally increased neuronal discharge resulting in transient episodes of sensory or motor neurological dysfunction, or psychic dysfunction. "To note, the methylation level in these NRSE regions, associated with DHX58 and HAAO, was homogeneous among children and adult control samples from PA Validation, reinforcing the possible link of the identified alterations with epilepsy." (PMID 37301955, 2023).
Insulin resistance (1 paper, 2020). Increased resistance towards insulin, that is, diminished effectiveness of insulin in reducing blood glucose levels. "Specifically, we demonstrated that in comparison to healthy controls, the overexpression of microbial proteins such as sprC, HAAO, and gbcA has a significant correlation with the insulin resistance of T2D individuals." (PMID 32214153, 2020).
learning disabilities (1 paper, 2021). "Our objective was to evaluate some aspects of tryptophan metabolism in ASD children (N = 45) compared to children with learning disabilities (N = 44) and healthy controls (N = 40) by measuring the expression levels of the MAOA, HAAO and AADAT genes using real-time RT-qPCR." (PMID 33767242, 2021). "In the current study, we measured the expression levels of three genes involved in tryptophan metabolic pathways, which are MAOA (serotonin pathway) along with two genes within the kynurenine pathway (HAAO and AADAT) in both children with ASD and learning disabilities." (PMID 33767242, 2021). "Relative to healthy control children, our data detected a significant decrease in the expression levels of MAAO, HAAO and AADAT genes among children with ASD, but indifferent expression levels in children with learning disabilities relative to both controls and ASD children." (PMID 33767242, 2021).
Parkinson disease (1 paper, 2017). A progressive degenerative disorder of the central nervous system characterized by loss of dopamine producing neurons in the substantia nigra and the presence of Lewy bodies in the substantia nigra and locus coeruleus. "Five to seven pQTL were observed for phosphoglycerate mutase 1 (PGAM1), the putative Parkinson disease autosomal recessive early onset 7 variant 1 (PARK7), triose phosphate isomerase (TPI1), peroxiredoxin 4 (PRDX4), malate dehydrogenase 1 (MDH1) and 3-hydroxyanthranilate 3,4-dioxygenase (HAAO)." (PMID 28424047, 2017).
peripheral nerve injury (1 paper, 2022). Injury to a peripheral nerve. "Similarly to what we found for the case of IDO1, HAAO was also identified in DCs that accumulate in the DRLs after peripheral nerve injury." (PMID 36227694, 2022).
Stroke (1 paper, 2021). Sudden impairment of blood flow to a part of the brain due to occlusion or rupture of an artery to the brain. "In accord with changes of metabolite levels, activities of KP enzymes differed as well: IDO1, KMO, 3-hydroxyanthranilate 3,4-dioxygenase (3-HAO) and the composed 3-HAO and aminocarboxymuconate semialdehyde decarboxylase (ACMSD) activity was higher in stroke patients compared to controls." (PMID 34680558, 2021).